GPR160 (G protein-coupled receptor 160)
Description:
Orphan receptor.
Synonyms: GPCR150; GPCR1
Tractability: Small molecule: it belongs to a druggable protein family. Antibody: its Gene Ontology location is reachable by antibodies, with high confidence; UniProt places it where antibodies can reach, with medium confidence; UniProt predicts a signal peptide or a membrane-spanning region; the Human Protein Atlas places it where antibodies can reach.
Target class: Family A G protein-coupled receptor; Membrane receptor
Gene: Protein-coding gene on chromosome 3 (170,037,451 to 170,089,944, forward strand). Ensembl gene ENSG00000173890.
Subcellular location: Cell membrane
Subcellular location (Human Protein Atlas): Plasma membrane
Gene Ontology:
Molecular function: protein binding
Cellular component: plasma membrane; receptor complex; membrane
Genetic constraint (gnomAD): Loss-of-function variants: 0 observed, 1.24 expected, observed/expected ratio (o/e) 0, 90% interval 0 to 1.65. That is too few expected variants to judge how well the gene tolerates losing a copy. Missense variants: 80 observed, 106.5 expected, observed/expected ratio (o/e) 0.75, 90% interval 0.63 to 0.9. Synonymous variants: 39 observed, 36.35 expected, observed/expected ratio (o/e) 1.07, 90% interval 0.83 to 1.4.
Homologues: Orthologues: chimpanzee GPR160 (99% identical), macaque GPR160 (96% identical), dog GPR160 (86% identical), pig GPR160 (84% identical), rabbit GPR160 (81% identical), guinea pig GPR160 (80% identical), mouse Gpr160 (66% identical), rat Gpr160 (65% identical), tropical clawed frog sec62 (37% identical), zebrafish gpr160 (22% identical).
Diseases named in the same sentence as GPR160 in open-access papers:
GPR160 is named in the same sentence as 21 diseases in open-access papers, as found by Europe PMC text mining. Sharing a sentence is not in itself a finding about the gene and the disease. The quoted sentences say what the papers report.
prostate carcinoma (6 papers, 2011 to 2025). A carcinoma that arises from epithelial cells of the prostate gland. "Our data suggest that the expression level of endogenous GPR160 is associated with the pathogenesis of prostate cancer." (PMID 26871479, 2016). "Analysis of DEGs between scramble- and ShGPR160-treated prostate cancer cells suggests that GPR160 is also associated with cytokine and cytokine receptor interaction." (PMID 26871479, 2016). "Information on GPR160 is scarce, but it has been reported to be a potential marker for prostate cancer, where it is involved in apoptosis and cell-cycle arrest." (PMID 38077141, 2023). "We compared the expression profile of a series of orphan GPCRs between normal prostate tissues and prostate cancer samples and found one of them, GPR160, showed different expression patterns." (PMID 26871479, 2016). "Knockdown of GPR160 by lentivirus-mediated short hairpin RNA constructs targeting human GPR160 gene (ShGPR160) resulted in prostate cancer cell apoptosis and growth arrest both in vitro and in athymic mice." (PMID 26871479, 2016). "Knockdown of GPR160 in prostate cancer cells increased the expression of caspase 1 and IL-6, induced cell cycle arrest and apoptosis, though the underlying molecular mechanism remains to be identified." (PMID 26871479, 2016). "A much higher level of GPR160 expression was observed in human prostate cancer cells such as PC-3, DU145, LNCaP and 22Rv1." (PMID 26871479, 2016). "The main objective of this study was to determine if GPR160 plays a role in the pathogenesis of prostate cancer." (PMID 26871479, 2016). "It was found that the GPR160 mRNA levels in all stages of prostate cancer samples were significantly higher than that of normal, but comparable among different cancer stages." (PMID 26871479, 2016). "To study the effect of GPR160 knockdown on the growth of prostate cancer cells, we produced a lentivirus system containing either scramble shRNA (scramble) or four different shRNAs targeting human GPR160 (ShGPR160-A, B, C and D)." (PMID 26871479, 2016). "GPR160 was found to be up-regulated in primary and metastatic prostate cancer samples (GEO accession GDS2546)." (PMID 26871479, 2016). "The transcription levels of GPR160 in the prostate cancer tissue samples and cell lines, such as PC-3, LNCaP, DU145 and 22Rv1 cells, were significantly higher than that seen in normal prostate tissue and cells." (PMID 26871479, 2016). "The aims of this study are to analyze the expression profile and cellular function of GPR160 in the context of target validation for prostate cancer." (PMID 26871479, 2016). "Taken together, our observations highlight GPR160 as a candidate target for the treatment of prostate cancer." (PMID 26871479, 2016). "NPY (neuropeptide Y) and GPR160 (G protein-coupled receptor 160) were among GPCRs with the highest prostatic tissue level and prostate cancer specificity index." (PMID 21443765, 2011). "Knockdown of GPR160 in prostate cancer cells increases apoptosis and growth arrest." (PMID 31765370, 2019). "In order to explore the mechanism by which GPR160 knockdown suppressed the growth of prostate cancer cells both in vivo and in vitro, Affymetrix GeneChip was applied to scramble- and ShGPR160-treated PC-3 cells to study changes of gene expression profile upon GPR160 silencing." (PMID 26871479, 2016). "This study investigates potential roles of GPR160, an orphan GPCR, in the pathogenesis of prostate cancer." (PMID 26871479, 2016). "It is suggested that GPR160 has a potential role in the pathogenesis of prostate cancer, but the ligand of GPR160 has not been discovered at this time." (PMID 41347146, 2025). "Investigation of transcription profiles of GPR160 demonstrated a marked increase of GPR160 mRNA levels in all stages of prostate cancer samples and cancer cell lines, but not in prostate hyperplasia tissues." (PMID 26871479, 2016).
prostate carcinoma (continued). "The targets identified based on the integrated analysis of CSMA data and publicly available transcriptomics data displayed high context specificity suggesting GPR160 and NPY likely to be the two most important GPCRs impacting on growth of human prostate and specifically prostate cancer cells." (PMID 21443765, 2011). "However, the specific mechanism of GPR160 in prostate cancer has not been revealed." (PMID 41347146, 2025). "Silencing of GPR160 was found to decrease viability of VCaP and LAPC-4 (p < .01) cells and moderately the viability of PC-3 prostate cancer cells (p < .05), but not RWPE-1, thus validating the rank product analysis based CSMA results." (PMID 21443765, 2011).
breast carcinoma (3 papers, 2013 to 2023). "Three of these genes belonged to the PAM50 set: AR, FOXA1, and GPR160, while the remaining genes had all been individually associated with breast cancer subtypes." (PMID 32605588, 2020). "Similar to FGFR4/ERBB2, the overall correlation between GPR160 and TMEM45B expression in TCGA breast cancers appeared in the lower spectrum (Spearman rho = 0.35)." (PMID 37857634, 2023).
Anxiety (2 papers, 2020 to 2024). Intense feelings of nervousness, tension, or panic often arise in response to interpersonal stresses. "Collectively, our observations suggest that mirroring the BCP-induced increase of GPR160 within the DRG elicits both anxiety-like behavior and enhanced nociceptive sensitivities." (PMID 39448865, 2024). "Pending confirmation of the activation of GPR160 by CARTp, research into the involvement of GPR160 in anxiety and mood-related behaviors could possibly uncover a relevant pharmacological target." (PMID 32599826, 2020). "Although the direct role of GPR160 in controlling depressive-like behavior has not been explored, there is evidence pointing at CARTp in the regulation of stress responses and anxiety." (PMID 32599826, 2020).
B cell acute lymphoblastic leukaemia (1 paper, 2024). "Furthermore, the top e2QTL for GPR160 upon TBOOH exposure represents a GWAS risk variant for testicular germ cell tumors (r2 = 0.824) and the e2QTL for PIP4K2A upon MMS exposure represents a GWAS risk variant for B cell acute lymphoblastic leukaemia (ALL) (r2 = 0.761)." (PMID 39623312, 2024).
bone cancer (1 paper, 2024). A primary or metastatic malignant neoplasm affecting the bone or articular cartilage. "Increased H3K27ac levels upon tumor infiltration enhance Sp1-mediated expression of the Gpr160 in dorsal root ganglia, which contributes to bone cancer pain." (PMID 39448865, 2024). "The identification of GPR160’s regulatory role in BCP provides potential targets for the prevention and treatment of bone cancer-related pain." (PMID 39448865, 2024).
Lewis lung carcinoma (1 paper, 2024). "We initiated the BCP model in both WT and Gpr160−/− mice via femoral infiltration of Lewis lung carcinoma (LLC) tumors." (PMID 39448865, 2024).
metastatic cancers (1 paper, 2016). A carcinoma which has spread from the original site of growth to another anatomic site. "Our data also suggest that GPR160 may represent a growing number of GPCRs that are up-regulated in primary and metastatic cancers to promote tumor formation." (PMID 26871479, 2016).
metastatic melanoma (1 paper, 2016). A melanoma that has spread from its primary site to another anatomic site. "This is consistent with a previous report showing up-regulation of GPR160 in cancerous prostate duct cells, CD4+CD56+ hematodermic neoplasm, metastatic melanoma and nasopharyngeal carcinoma cells." (PMID 26871479, 2016). "Amplification of GPR160 at 3q26.2-q26.32 was also detected in two nasopharyngeal carcinoma cell lines, an observation consistent with that seen in metastatic melanoma as opposed to benign samples." (PMID 26871479, 2016).
neuropathic pain (1 paper, 2021). Chronic pain caused by damage to nerve fibers. "In the recent studies discussed here, CARTp and GPR160 are implicated in neuropathic pain and food and water intake." (PMID 38410642, 2021).
prostatitis (1 paper, 2016). An infectious or non-infectious inflammatory process affecting the prostate gland. "The less than normal level of GPR160 presence in prostatitis tissues remains to be confirmed with additional tissue samples." (PMID 26871479, 2016). "The average GPR160 transcription level in prostate hyperplasia tissues was similar to that of normal but in prostatitis tissue samples it was lower than normal, though no statistical significance was noted due to a small sample size (n = 3)." (PMID 26871479, 2016).
psoriasis (1 paper, 2015). An autoimmune condition characterized by red, well-delineated plaques with silvery scales that are usually on the extensor surfaces and scalp. "In addition, four new susceptibility genes (C1orf141, GPR160, CCDC129 and AP5B1) with unknown functions in the pathogenesis of psoriasis were also identified, indicating that additional molecular mechanisms contribute to the risk of developing psoriasis." (PMID 25854761, 2015).
testicular germ cell tumor (1 paper, 2024). A germ cell tumor arising from the testis. "Moreover, we found an increased expression of GPR160 and PIP4K2A among carriers of GWAS risk variants for testicular germ cell tumors and B cell ALL." (PMID 39623312, 2024).
viral infection (1 paper, 2016). "Expression of both CASP1 and IL6 genes could be induced not only by viral infection directly but also by GPR160 siRNAs in a virus-free transient transfection system." (PMID 26871479, 2016).
cancer (6 papers, 2011 to 2024). A tumor composed of atypical neoplastic, often pleomorphic cells that invade other tissues. "In the cell morphology and connective tissue-associated cancer network, Ubc (ubiquitin C) is directly connected to all but three genes of interest (Bnipl, Gpr160, and Klhl8)." (PMID 25474466, 2014). "Putative CART peptide receptor GPR160 was implicated recently in the pathogenesis of cancer." (PMID 37373130, 2023). "Accumulating evidence suggests the association of GPR160 with cancer." (PMID 37373130, 2023). "In KATO cancer cells, CARTp-induced cFOS expression and this was blocked by prior depletion of GPR160 using an si-GPR160." (PMID 38410642, 2021). "The level of GPR160 was comparable in prostate samples collected from stages II to IV cancer patients." (PMID 26871479, 2016). "Up-regulation of GPR160 transcription was found in many human cancer cell lines or tissue samples." (PMID 26871479, 2016). "Since this was seen in both androgen-dependent and androgen-independent cancer cell lines, we postulate that the effect of GPR160 does not require the participation of androgen receptors." (PMID 26871479, 2016).
tumor (3 papers, 2016 to 2024). "To explore this, we initially assessed the impact of suppressing the elevated levels of GPR160 in the DRG on the development of pain hypersensitivity induced by tumor infiltration." (PMID 39448865, 2024). "Our findings consistently demonstrate an upregulation of Gpr160 mRNA and protein in injured DRG neurons following tumor infiltration, suggesting a significant role for GPR160 in the development and maintenance of BCP." (PMID 39448865, 2024). "Collectively, these observations indicate that tumor infiltration induces a reduction in H3K27me3 and an increase in H3K27ac modifications, consequently enhancing the transcriptional activation of GPR160 and contributing to the mediation of BCP." (PMID 39448865, 2024). "In this study, we provide preliminary evidence that tumor infiltration leads to an upregulation of GPR160 expression through Sp1-mediated activation in injured DRG neurons." (PMID 39448865, 2024). "Subsequently, to elucidate the modulatory influence of H3K27me3 and H3K27ac on GPR160, we evaluated GPR160 expression after tumor infiltration." (PMID 39448865, 2024). "We observed a significant and sustained upregulation of GPR160 in rat DRG neurons following tumor infiltration." (PMID 39448865, 2024). "Among the oGPCRs identified, GPR160 has emerged as one of the top eight upregulated genes in DRGs at 12 days post-tumor infiltration." (PMID 39448865, 2024). "Here, we profile orphan G protein-coupled receptors in the dorsal root ganglia (DRG) following tumor infiltration, and observe a notable increase in GPR160 expression." (PMID 39448865, 2024). "The modulation of histone modifications serves to enhance the binding capacity of the transcription factor Sp1 to the Gpr160 gene promoter, consequently increasing GPR160 expression following tumor infiltration." (PMID 39448865, 2024). "Almost all mice developed tumors within 42 days after inoculation, however, the silencing of GPR160 impaired tumor growth." (PMID 26871479, 2016). "As anticipated, the GPR160 protein levels on POD 18 were notably diminished in the ipsilateral DRG of rats subjected to AAV2/9-Gpr160 shRNA microinjections conducted 28 and 16 days prior to tumor cell injection, in comparison to those microinjected with AAV2/9-Scr shRNA (Fig. EV3D–G)." (PMID 39448865, 2024). "Consistently, a notable mitigation of mechanical allodynia, heat hyperalgesia, and cold allodynia was observed on days 12 and 14 following tumor infiltration on the ipsilateral side in rats treated with Gpr160 siRNA, as compared to those treated with scrambled siRNA (Fig. EV2H–J)." (PMID 39448865, 2024). "How does GPR160 exhibit upregulation within the DRG subsequent to tumor infiltration?" (PMID 39448865, 2024). "Intriguingly, orphan GPR160 was significantly upregulated in DRGs following tumor infiltration." (PMID 39448865, 2024). "Tumor infiltration results in reduced H3K27me3 and increased H3K27ac modifications, enhanced binding of the transcription activator Sp1 to the Gpr160 gene promoter region, and induction of GPR160 expression." (PMID 39448865, 2024). "Furthermore, we investigated whether the increased DRG GPR160 alone was adequate to induce nociceptive hypersensitivity due to tumor infiltration." (PMID 39448865, 2024). "Tumor infiltration increases DRG neuron excitability in wild-type mice, but not in Gpr160 gene knockout mice." (PMID 39448865, 2024).
infection (2 papers, 2016 to 2024). The state of being infected such as from the introduction of a foreign agent such as serum, vaccine, antigenic substance or organism. "This line of research may help us reveal the role of GPR160 in infection and inflammation." (PMID 26871479, 2016). "Polyomaviruses, flaviviruses, influenza virus, and SARS-CoV-2 activate and/or require GPCR-mediated pathways for cell infection, including MAPK, suggesting that GPR160 could become an attractive target for the development of broad CD antiviral therapies." (PMID 39791702, 2024).
GPR160 also shares sentences with these, for which no sentence is quoted: adenocarcinoma (1 paper); brain cancer (1); colon cancer (1); nasopharyngeal carcinoma (1); ovarian carcinoma (1).